MTA3 (metastasis associated 1 family member 3)
Diseases named in the same sentence as MTA3 in open-access papers (continued):
Sharing a sentence is not in itself a finding about the gene and the disease.
non-small cell lung carcinoma (7 papers, 2013 to 2025). A group of at least three distinct histological types of lung cancer, including non-small cell squamous cell carcinoma, adenocarcinoma, and large cell carcinoma. "Studies have shown that miR-495 can target metastasis-associated protein 3 (MTA3), which is overexpressed in non-small cell lung cancer." (PMID 31185898, 2019). "MTA3, functioning as an oncogene, is critically implicated in the pathogenesis of non-small cell lung cancer (NSCLC) and may have a potential association with anti-tumor immunity." (PMID 41584603, 2025). "In addition, MTA3 overexpression is associated with the pTNM stage, nodal metastasis, and poor prognosis in patients with non-small-cell lung cancer." (PMID 36050478, 2022). "The objective of the current study was to investigate the expression pattern and clinicopathological significance of MTA3 in patients with non-small cell lung cancer (NSCLC)." (PMID 23840517, 2013). "In nonhormone cancers, the MTA3 mRNA and protein levels are higher in non-small-cell lung cancer tissues metastasized to the lymph node." (PMID 36050478, 2022).
lung carcinoma (6 papers, 2013 to 2020). "In addition, we explored the association of MTA3 with cell proliferation in several lung cancer cell lines." (PMID 23840517, 2013). "Previous studies have found that miR-495 targets MTA3 in the regulation of lung cancer growth and migration." (PMID 32927434, 2020). "MTA3 was overexpressed in 62 of 108 (57.4%) human lung cancer samples and correlated with p-TNM stage (p<0.0001), nodal metastasis (p = 0.0009) and poor prognosis (p<0.05)." (PMID 23840517, 2013). "Together, these results suggest that inhibiting MTA3 expression induces cell cycle arrest at the G1-S transition, suppressing lung cancer cell growth." (PMID 23840517, 2013). "This was in accordance with previous data that has suggested that MTA3 plays an important role in lung cancer progression." (PMID 23840517, 2013). "To validate the potential role of MTA3 in lung cancer development, we first checked its expression level in several cell lines and used A549 and H157 cells (with relatively high MTA3 levels) for further studies." (PMID 23840517, 2013). "We found that the level of MTA3 expression in H157 and A549 cells was higher than other cell lines.To explore the biological function of MTA3 in lung cancer cells, we employed siRNA to knockdown MTA3 expression in both H157 and A549 cell lines." (PMID 23840517, 2013). "We further analyzed the relationship between MTA3 protein expression and the prognosis of lung cancer patients and found that MTA3 overexpression correlated with a reduction in overall survival (p<0.05)." (PMID 23840517, 2013). "The expression of MTA3 was analyzed through Western blotting and realtime PCR in a panel of lung cancer cell lines." (PMID 23840517, 2013). "Furthermore, MTA3 was found to be a target of miR-495, which inhibited proliferation and migration in lung cancer cells." (PMID 28279208, 2017). "The inhibition of the G1 to S transition in cell cycle progression might explain the mechanisms behind MTA3 effects on lung cancer cell proliferation." (PMID 23840517, 2013). "Colony formation analysis showed that the depletion of MTA3 in H157 and A549 cells led to a significant reduction in the number and size of foci (A549 control vs MTA3si: 275±7 vs 81±10; H157 control vs MTA3si: 476±10 vs 276±32), suggesting that MTA3 modulates the proliferation of lung cancer cells." (PMID 23840517, 2013). "Importantly, we were able to show that MTA3 correlates with the poor survival of lung cancer patients." (PMID 23840517, 2013). "However, the protein expression of MTA3 in primary lung cancer and its relationship with clinicopathological factors has not been examined." (PMID 23840517, 2013). "In addition, the depletion of MTA3 expression with small interfering RNAs inhibited cell growth and colony formation in the A549 and H157 lung cancer cell lines." (PMID 23840517, 2013). "Thus, miR-495 targeting of MTA3 may be involved in the regulation of lung cancer growth and migration." (PMID 31185898, 2019). "Therefore, the biological roles of MTA3 in lung cancer cells are still unclear." (PMID 23840517, 2013). "Thus, our study suggests that MTA3 functions as an oncogene in lung cancer development." (PMID 23840517, 2013). "Thus, our results showing decreased levels of cyclin A, D1, and p-Rb correlate with the decreased levels of cells in the S and G2 phase and the increased levels of cells in the G1 phase after MTA3 knockdown, suggesting MTA3 plays an important role in cell cycle control of lung cancer cells." (PMID 23840517, 2013). "However, expression of MAT3 in primary lung cancer and its relationship with clinicopathological factors have not been examined and the biological roles of MTA3 in lung cancer cells are still unclear." (PMID 24107548, 2013). "However, the expression pattern of MTA3 as well as its correlation with clinical and pathological factors had not yet been defined in human lung cancer." (PMID 23840517, 2013).
lung carcinoma (continued). "However, expression of MTA3 mRNA and protein in primary lung cancer and its relationship with clinicopathological factors has not been examined and the biological roles of MTA3 in lung cancer cells are still unclear." (PMID 24107548, 2013).
Breast Tumors (4 papers, 2011 to 2020). "The MTA3 (Downregulated of MTA-3 in ER-negative Breast Tumors) pathway was associated (positively correlated) with two predicted IC50 vectors belong to L-685458(gamma-secretase) and PD-0332991(CDK4/6) drugs." (PMID 32174963, 2020). "As the TCGA data shows, the mRNA level of the MTA family, containing MTA1, MTA2 and MTA3, is higher in breast tumor tissues than in normal tissues (p=1e-12 in MTA1, p=9.7e-9 in MTA2, p<2.22e-16 in MTA3)." (PMID 33282725, 2020). "Immunoreactivity for MTA3 also correlated with ER-ve status of breast tumours and lack of E-cadherin." (PMID 21713035, 2011).
endometrial cancer (4 papers, 2013 to 2021). Primary or metastatic malignant neoplasm involving the endometrium (mucous membrane that lines the endometrial cavity). "Metastasis tumor antigen 3 (MTA3) is a member of a cancer progression-related protein family and has been found to be associated with lymph node involvement and lymphovascular space invasion in uterine non-endometrial cancer." (PMID 30947262, 2019). "In contrast to its underexpression in endometrioid carcinomas, MTA3 was found to be overexpressed in uterine non-endometrial cancer." (PMID 28279208, 2017).
GEJ adenocarcinoma (4 papers, 2013 to 2025). "Thus, the analysis indicates that expression of MTA3-pathway components is strongly associated with the survival of GEJ adenocarcinoma patients." (PMID 23671646, 2013). "However, we found that, in GEJ adenocarcinoma, the loss of MTA3 was associated with several clinicopathologic indicators, including poor tumor differentiation, advanced disease stage, lymph node and distant metastasis, increased Snail expression, and decreased E-cadherin expression." (PMID 23671646, 2013). "In GEJ adenocarcinoma, the components of the MTA3 pathway were proved to be of prognostic significance." (PMID 28279208, 2017). "To evaluate the prognostic impacts of MTA3-pathway components on the outcomes of patients with GEJ adenocarcinoma, we performed Kaplan-Meier survival analyses." (PMID 23671646, 2013). "Given that evidenced functions of MTA3 as a transcriptional corepressor and tumor suppressor, we determine if MTA3 is downregulated in GEJ adenocarcinoma." (PMID 23671646, 2013). "Taken together, these observations clearly suggest that MTA3-regulated EMT pathway is altered in GEJ adenocarcinoma." (PMID 23671646, 2013). "Relationship between MTA3 expression and clinicopathologic variables in tissue samples of GEJ adenocarcinoma (n = 128)." (PMID 23671646, 2013). "We examined MTA3 expression at protein level in a cohort of GEJ adenocarcinoma specimen (n = 25) by immunoblot analysis, and transcript level of MTA3 on microarray database." (PMID 23671646, 2013). "Protein expression of MTA3, Snail and E-cadherin was assayed in a cohort of 128 primary GEJ adenocarcinoma." (PMID 23671646, 2013). "Relationship between combined expression patterns of MTA3, Snail, and E-cadherin (MTA3−/Snail+/E-cadherin- vs. other expression patterns) and clinicopathologic variables in tissue samples of GEJ adenocarcinoma (n = 128)." (PMID 23671646, 2013). "Our results also suggest that MTA3 expression is independent prognostic factors in GEJ adenocarcinoma." (PMID 23671646, 2013). "Here, we evaluated the expression pattern of the components of MTA3 pathway and the corresponding prognostic significance in GEJ adenocarcinoma." (PMID 23671646, 2013). "We next assessed the correlation of MTA3 expression with the clinicopathological features in GEJ adenocarcinoma." (PMID 23671646, 2013). "However, mRNA and protein expression of MTA3 were significantly downregulated in esophageal squamous cell carcinoma and esophagogastric adenocarcinoma, a finding consistently validated across multiple independent databases and clinical cohorts." (PMID 41584603, 2025). "Future research should aim to elucidate the epigenetic mechanisms governing MTA3 expression in GEJ adenocarcinoma, validate its clinical utility as a prognostic biomarker, and develop targeted therapeutic strategies for the MTA3/Snail/E-cadherin signaling pathway." (PMID 41584603, 2025). "Further evaluation of the MTA3-modulated EMT pathway may increase our ability to assess prognosis in patients with GEJ adenocarcinoma." (PMID 23671646, 2013). "Therefore, in this study we examined the protein expression of the EMT regulators MTA3, Snail, and E-cadherin specifically in GEJ adenocarcinoma." (PMID 23671646, 2013). "To test possibility that MTA3 may be served as a prognostic predictor for GEJ adenocarcinoma patients, we applied univariate and multivariate Cox-regression models for further analysis." (PMID 23671646, 2013). "Interestingly, OE-19, the exclusive GEJ adenocarcinoma cell line which has high metastatic potential, had lower levels of MTA3 mRNA expression compared to most other gastric and esophageal adenocarcinoma cell lines." (PMID 23671646, 2013). "Accordingly, these results consistently indicate that MTA3 is downregulated in tumorous tissues, and underexpression of MTA3 is related with stronger metastasis tendency in tumor cells, supporting the hypothesis that MTA3 may act as a tumor suppressor and metastasis inhibitor in GEJ adenocarcinoma." (PMID 23671646, 2013).
GEJ adenocarcinoma (continued). "Our results indicate that the MTA3-regulated EMT pathway is altered to favor EMT in GEJ adenocarcinoma and that MTA3 expression is an independent prognostic factor in patients with GEJ adenocarcinoma." (PMID 23671646, 2013). "To obtain the functional insight into MTA3 in EMT and tumor progression of GEJ adenocarcinoma, we characterized the expression profile of MTA3-pathway components in GEJ adenocarcinoma." (PMID 23671646, 2013). "Taken together, the results suggest that MTA3 and the EMT pathway regulators Snail and E-cadherin have a substantial role in the metastasis and progression of GEJ adenocarcinoma." (PMID 23671646, 2013). "The frequent lack of MTA3 expression in GEJ adenocarcinoma that we observed is consistent with its essential role in EMT as reported in breast, endometrial, and ovarian cancers." (PMID 23671646, 2013). "Collectively, results suggest that the MTA3-regulated EMT pathway is altered to favor EMT and, therefore, disease progression and that MTA3 expression was an independent prognostic factor in patients with GEJ adenocarcinoma." (PMID 23671646, 2013).
hepatocellular carcinoma (4 papers, 2019 to 2026). A malignant tumor that arises from hepatocytes. "Catalpol inhibited the invasion of hepatocellular carcinoma cells by regulating the miR-22-3p/MTA3 axis; moreover, the expression of miR-140-5p was also found to be associated with inhibition of the invasion and migration of hepatocellular carcinoma cells." (PMID 34578851, 2021).
lymph node metastasis (4 papers, 2013 to 2025). "Logistic regression analysis indicated that the relative expression level of MTA3 mRNA was a risk factor of lymph node metastasis in the patients with NSCLC (Wald χ2 = 7.493, P = 0.006)." (PMID 24107548, 2013). "Elevated MTA3 levels in these aggressive variants are significantly associated with advanced surgical stage, lymph node metastasis, lymphovascular space invasion, and reduced progression-free and overall survival, establishing MTA3 as an independent prognostic factor." (PMID 41584603, 2025). "MTA3 overexpression was positively associated with high International Federation of Gynecology and Obstetrics (FIGO) surgical stage, lymph node metastasis, and lymphovascular space invasion (LVSI)." (PMID 28279208, 2017). "It has been observed that MTA3 was overexpressed in NSCLC tissue, which can serve as a risk factor for lymph node metastasis." (PMID 28279208, 2017). "Multivariate analysis confirmed that MTA3 expression independently affects prognosis, with predictive power comparable to established factors, including tumor differentiation grade, depth of invasion, lymph node metastasis, and TNM stage." (PMID 41584603, 2025). "MTA3 mRNA is over-expressed in NSCLC samples and is a risk factor of lymph node metastasis." (PMID 24107548, 2013). "In this study, a lack of MTA3 expression was also associated with poor OS in patients without lymph node metastasis." (PMID 23671646, 2013). "Elevated MTA3 expression is associated with favorable clinicopathological characteristics, including well-to-moderately differentiated histology, earlier disease stages (I/II), and absence of lymph node metastasis." (PMID 41584603, 2025). "However, the multivariate analysis indicated that lymph node metastasis (HR 2.185; 95% CI 1.276 to 3.740; P = 0.004), male sex (HR 1.782; 95% CI 1.061 to 2.993; P = 0.029), and MTA3 expression (HR 0.442; 95% CI 0.275 to 0.708; P = 0.001) were independent prognostic factors." (PMID 23671646, 2013). "An analysis of the relationship between MTA3 expression and OS was performed separately in patients with lymph node metastasis (N1) and in patients without lymph node metastasis (N0)." (PMID 23671646, 2013).
ovarian carcinoma (4 papers, 2013 to 2025). A malignant neoplasm originating from the surface ovarian epithelium. "MTA1 overexpression in metastatic ovarian cancer tissues is associated with downregulation of MTA3 and E-cadherin in tumor cells." (PMID 41584603, 2025). "Reduced MTA3 expression has been reported to be associated with poor differentiation in endometrioid adenocarcinomas but not with any clinicopathologic indicators of ovarian cancer." (PMID 23671646, 2013).
colorectal cancer (3 papers, 2017 to 2019). A primary or metastatic malignant neoplasm that affects the colon or rectum. "In the present study, we demonstrated that MTA3 expression level in human colorectal cancer was down-regulated and significantly associated with tumor differentiation, invasion and metastasis." (PMID 28418887, 2017). "Due to statistical analysis revealed a significant association between MTA3 level and tumor aggressiveness, we next investigated the association of MTA3 level in colorectal cancer with disease-free survival which depended on tumor invasion and metastasis." (PMID 28418887, 2017). "As results showed a decreased expression pattern of MTA3, we further investigated the association of MTA3 level in colorectal cancer with clinicopathologic characteristics of patients involved." (PMID 28418887, 2017). "Statistical analysis revealed that low MTA3 expression level in colorectal cancer was significantly associated with poor differentiation, node metastasis, distant metastases and advanced TNM stage." (PMID 28418887, 2017). "Since univariate and multivariate analysis demonstrated that patients with MTA3 negative tumors had higher risk of tumor recurrence, we next carried out statistical analysis to investigate the association of MTA3 level in colorectal cancer with overall survival of patients." (PMID 28418887, 2017). "Therefore, we conducted the present study to determine MTA3 expression level and its association with clinicopathologic characteristics, disease-free survival and overall survival of patients with colorectal cancer." (PMID 28418887, 2017). "In other carcinomas such as hepatocellular, lung, gastric, and colorectal cancers, MTA3 is reported to be overexpressed, with higher expression correlated with tumor progression and poorer prognosis." (PMID 31149338, 2019). "Our study also proved for the first time that MTA3 was independently correlated to disease-free and overall survival of patients with colorectal cancer." (PMID 28418887, 2017). "Results based on MTA3 staining classification proved that MTA3 level in colorectal cancer was down-regulated compared with that in normal tissues." (PMID 28418887, 2017). "Results showed that MTA3 expression in colorectal cancer was significantly decreased in colorectal cancer compared with normal specimens." (PMID 28418887, 2017). "In our study cohort, it was proved that low MTA3 level in colorectal cancer was correlated to unfavorable disease-free and overall survival." (PMID 28418887, 2017). "The results above suggested that patients with MTA3 negative colorectal cancer would have higher risk of tumor relapse than those with MTA3 positive ones." (PMID 28418887, 2017). "However, further studies are still needed to explore the molecular mechanism of MTA3 in colorectal cancer." (PMID 28418887, 2017). "While 61 cases were defined as positive MTA3 staining in the 239 cases of colorectal cancer." (PMID 28418887, 2017). "However, till now, the expression level and potential function of MTA3 remains unclear in colorectal cancer." (PMID 28418887, 2017). "According to the immunohistochemical staining evaluation protocol described in methods, negative MTA3 staining was detected in 178 colorectal cancer specimens." (PMID 28418887, 2017). "Based on staining classification, results of statistical analysis showed that the negative rate of MTA3 in colorectal cancer specimens was significantly increased, compared with that in normal control specimens (P < 0.05)." (PMID 28418887, 2017). "While the expression pattern and potential function of MTA3 in colorectal cancer has not been addressed yet." (PMID 28418887, 2017). "In colorectal cancer, negative MTA3 staining was more likely to be detected in tumors with poor differentiation, node metastasis, distant metastases or advanced TNM stage in our investigation." (PMID 28418887, 2017).
colorectal cancer (continued). "Kaplan–Meier analysis proved that MTA3 was associated with both disease-free survival and overall survival of patients with colorectal cancer that patients with negative MTA3 expression tend to have unfavorable outcome." (PMID 28418887, 2017).
diffuse large B-cell lymphoma (3 papers, 2020 to 2023). "In diffuse large B cell lymphoma (DLBCL), MTA3 associates with an oncogenic transcription repressor, BCL6, which plays a significant role in the development of a significant proportion of DLBCL." (PMID 37509346, 2023). "For instance, the NuRD complex subunit MTA3 has been shown to directly interact with BCL-6, an oncogene that plays a crucial role in DLBCL (diffuse large B cell lymphoma)." (PMID 32070428, 2020). "The MTA3 subunit of the NuRD complex interacts with BCL-6, an oncogene that has transformative potential in diffuse large B-cell lymphoma (DLBCL)." (PMID 37046781, 2023).